PTH (parathyroid hormone)
Diseases named in the same sentence as PTH in open-access papers (continued):
Sharing a sentence is not in itself a finding about the gene and the disease.
hypoparathyroidism (continued). "By 6 months postoperatively, PTH levels had normalized in all patients, with no instances of permanent hypoparathyroidism observed." (PMID 40066709, 2025). "Hypoparathyroidism (HPT) is a common complication after thyroid surgery, the most significant predictors of which were found to be the extent of surgery and a low immediate postoperative PTH level." (PMID 40217886, 2025). "The latest clinical guidelines for the evaluation and management of hypoparathyroidism suggest the use of PTH replacement therapy in patients who are not adequately controlled with conventional therapy." (PMID 40869557, 2025). "Our results support the efficacy of subtotal PTX in reducing PTH levels without leading to overt hypoparathyroidism, reinforcing the importance of preserving well-vascularized parathyroid tissue to mitigate post-PTX complications." (PMID 41597072, 2025). "Although some glands connected by minimal fibrous tissue exhibited signs of ischemia or congestion during surgery, long-term postoperative PTH levels did not reveal an increased incidence of permanent hypoparathyroidism." (PMID 40066709, 2025). "Our data show a negative correlation between preoperative serum PTH levels and RBP, and univariate analysis identified high RBP levels as a risk factor for postoperative hypoparathyroidism." (PMID 40969367, 2025). "Measuring preoperative PTH values and estimating the decline in PTH does not add value to the prediction of postsurgical hypoparathyroidism." (PMID 38478048, 2024). "The PTH levels of all patients recovered to within the normal range and permanent hypoparathyroidism occurred only in patients without PA." (PMID 39022344, 2024). "Although effective, PTH replacement is still not a viable option for hypoparathyroidism therapy; therefore, replacing calcium and the active form of vitamin D (1,25-dihydroxyvitaminD) are necessary." (PMID 38578437, 2024). "It is worth noting that synthetic PTH treatment has not yet been approved for chronic hypoparathyroidism in children." (PMID 39246904, 2024). "Hypoparathyroidism is a rare endocrine disorder characterized by low or absent secretion of parathyroid hormone (PTH), which leads to decreased calcium and increased phosphorus levels in the serum." (PMID 37819413, 2024). "However, the antiresorptive effect of GIP is preserved in overweight or hypoparathyroidism individuals, suggesting that GIP affects bone metabolism independently of PTH." (PMID 38725663, 2024). "A significant association was found between the type of surgery and the occurrence of postoperative hypoparathyroidism as patients who underwent total thyroidectomy without neck dissection were most likely to have postoperative low PTH levels (p=<0.05)." (PMID 38646308, 2024). "Although no symptoms of hypoparathyroidism were observed and the blood calcium and other biochemical indicators remained within their respective ideal levels, the low postoperative PTH levels were detrimental to the long-term survival of the patients." (PMID 36331700, 2023). "In hypoparathyroidism, lack of parathyroid hormone (PTH) leads to low calcium levels and decreased bone remodeling." (PMID 38130746, 2023). "Conversely, of the 329 patients not treated for hypoparathyroidism, 37 (11.3 per cent) had a low PTH level, and 292 had a normal or high PTH level." (PMID 37758507, 2023). "In patients with Hypoparathyroidism, the lack of PTH has a profound effect on calcium homeostasis, which is only partially restored by the classical treatment with calcium and vitamin D active analogues." (PMID 37240884, 2023). "PTH is also a regulator of bone structure and remodeling, and it was previously thought that in the absence of PTH in hypoparathyroidism, the incidence of fractures decreases due to increased bone mass and decreased remodeling." (PMID 35885858, 2022). "In hypoparathyroidism, the lack of PTH action increases the activity of NaP2a and NaP2c, increasing renal resorption of phosphate." (PMID 36382754, 2022).
hypoparathyroidism (continued). "Following postoperative PTH reduction (though without significant rates of overt postoperative hypoparathyroidism), these patients' skeletal system is immediately allowed to retain more calcium." (PMID 34564834, 2022). "Hypoparathyroidism is an endocrine disorder in which parathyroid hormone (PTH) production is abnormally low or absent." (PMID 35885858, 2022). "No patients developed permanent hypoparathyroidism in either group, and the PTH levels of all patients who suffered transient hypoparathyroidism increased to the normal reference range during the follow-up period." (PMID 35784544, 2022). "Some studies reported that patients with at least one well-perfused gland had normal postoperative PTH levels (in the presence of postoperative hypoparathyroidism with a 100% negative predictive value)." (PMID 35813620, 2022). "Hypoparathyroidism (HP) is a rare endocrine disorder characterized by absent or inappropriately low levels of circulating parathyroid hormone (PTH)." (PMID 32833143, 2021). "Unlike other hormonal insufficiencies, permanent hypoparathyroidism is not treated through replacement therapy with PTH in Australia, although it has recently been approved in the United States for refractory cases." (PMID 33498810, 2021). "Parathyroid hormone (PTH) became the gold standard in the diagnosis of postoperative hypoparathyroidism in recent years, and has not been performed in all cases in this study." (PMID 33897619, 2021). "Their findings showed that the ICGA score was predictive of postoperative PTH levels, as all of the 22 patients with at least one PG having an ICG score of 2 (84.6%) had normal postoperative PTH levels, while half of those with poor vascularization on ICGA developed transient hypoparathyroidism." (PMID 34359693, 2021). "One patient with recurrent MTC had permanent hypoparathyroidism before surgery but had no significant change in parathyroid hormone (PTH) levels after surgery (5.2 pg/ml vs. 5.1 pg/ml)." (PMID 34407789, 2021). "None of the patients had symptoms of hypoparathyroidism, and none of those who underwent PTH testing during the postoperative period had a PTH level lower than 27 pg." (PMID 34762781, 2021). "In patients without hypoparathyroidism, periodic measurement of calcium and intact parathyroid hormone levels can help prevent unsuspected acute hypocalcemic seizures and/or tetany." (PMID 34790633, 2021). "Recently, treatment involving injections of recombinant parathyroid hormone has been recommended in hypoparathyroidism that does not respond to conventional therapy." (PMID 34194389, 2021). "Another limitation is that we evaluated the calcium and PTH within 2 weeks after total thyroidectomy only, so this study does not differentiate between temporary or permanent hypoparathyroidism." (PMID 33868401, 2021). "Hypoparathyroidism is an endocrine disorder characterized by low serum calcium levels, high serum phosphorus levels, and by inappropriate or absent secretion of the parathyroid hormone (PTH)." (PMID 34638612, 2021). "Absent or decreased serum parathyroid hormone (PTH), confirms hypoparathyroidism as the cause of hypocalcemic symptoms." (PMID 32714707, 2020). "Magnesium deficiency should always be ruled out, as it can induce reversible PTH resistance, producing the clinical manifestations of hypoparathyroidism." (PMID 33133833, 2020). "Surgical method, previous neck surgery overall, lymphadenectomy, thyroid volume and preoperative TSH and PTH levels, however, showed no significant influence on postoperative hypoparathyroidism." (PMID 33322553, 2020). "Higher PWV in the non-surgical hypoparathyroidism group where mean PTH level is lower is in line with our study." (PMID 32267362, 2020). "In our study, the negative correlation between the PTH level and the disulfide and disulfide/thiol ratios showed that hypoparathyroidism is a state of oxidative stress." (PMID 33033457, 2020).
hypoparathyroidism (continued). "Hypoparathyroidism is a rare endocrine disorder in which the production of parathyroid hormone (PTH) by the parathyroid gland is absent or inappropriately low1,2." (PMID 32765831, 2020). "Hence, future clinical trials are suggested on patients with hypoparathyroidism before treatment to investigate the FGF23 functions and its interaction with PTH more accurately, considering tissue iron evaluation e.g. in liver." (PMID 33198660, 2020). "The secondary outcome is hypoparathyroidism, defined as the PTH level from the non-grafted forearms being less than 15 pg/ml (normal range 15–65 pg/ml)." (PMID 30704522, 2019). "Hypoparathyroidism is a rare endocrine disease which is characterized by hypocalcaemia because of inappropriately low or absent levels of parathyroid hormone." (PMID 31406522, 2019). "In the absence of PTH, urinary calcium excretion is elevated and contributes to the long-term complications of hypoparathyroidism which include renal insufficiency, nephrocalcinosis as well as nephrolithiasis." (PMID 30540559, 2019). "Of note, the definite calcium and PTH values for diagnosis of hypoparathyroidism have not been defined yet." (PMID 29694629, 2018). "Hypoparathyroidism (corrected serum Ca 7.5-8.4 mg/dL and no elevation of PTH) was found in 25 of 66 (38%) thalassemic patients." (PMID 29726397, 2018). "There was no permanent hypoparathyroidism, which was defined as persistently low blood calcium levels (< 2 mmol/L) and subnormal parathyroid hormone levels by 6 months after surgery." (PMID 29108371, 2017). "One study focused on two large unrelated families counting a total of 15 living patients with autosomal dominant isolated hypoparathyroidism, in whom mutations in the genes encoding the CASR, PTH, and GCM2 were ruled out." (PMID 27803672, 2016). "For human primary hypoparathyroidism, this means that the animal model should demonstrate not only low PTH levels, but also comparable changes in the calcium and phosphorus balance." (PMID 27695051, 2016). "Hypoparathyroidism is a rare endocrine disorder in which parathyroid hormone (PTH) production is abnormally low or absent, resulting in low serum calcium and increased serum phosphorus." (PMID 28138323, 2016). "The lack of endogenous parathyroid hormone secretion due to post-surgical hypoparathyroidism abolished the physiological mechanism that compensates the reduced calcium absorption, which was a challenge for us to overcome." (PMID 25348653, 2014). "The PTH-SC level was not significantly different between those who eventually developed temporary or permanent hypoparathyroidism (p = 0.295)." (PMID 22399155, 2012). "Although routine measurement of PTH following thyroidectomy is not available at our service, hypoparathyroidism can be suspected when there is a drop in calcium levels, especially when patients require oral supplementation." (PMID 21181066, 2010). "Furthermore, standardized PTH cutoff points have not been established, and improved follow-up strategies for hypoparathyroidism classification as permanent, based on well-defined diagnostic criteria, are needed." (PMID 40671592, 2026). "Fourth, we defined hypoparathyroidism based on PTH rather than calcium levels." (PMID 40979704, 2025). "The study suggests that ICG perfusion might predict which patients are unlikely to develop hypoparathyroidism after surgery, potentially reducing the need for routine calcium and parathyroid hormone (PTH) level checks after surgery in these patients." (PMID 40550518, 2025). "In hypoparathyroidism, bone turnover is significantly reduced due to the absence of PTH." (PMID 41211056, 2025). "Indeed, all identified patients developed persistent primary hypoparathyroidism and the measurements of PTH did not recover many months after the initial diagnosis." (PMID 40356787, 2025).
hypoparathyroidism (continued). "Additionally, PTH levels were normal for all patients who underwent surgery with NIRAF one month after the procedure, whereas one patient in the control group was diagnosed with permanent hypoparathyroidism." (PMID 41303822, 2025). "Moreover, the absence of PTH results in abnormal bone remodeling and contributes to reduced quality of life for many hypoparathyroidism patients despite adhering to conventional therapy." (PMID 40177730, 2025). "The potential reason for this finding could be that alcohol can lead to a transient and reversible decrease in PTH secretion, while the exact mechanism of hypoparathyroidism in patients with liver cirrhosis is not clear." (PMID 38472981, 2024). "Nevertheless, single or even multiple daily injections of the medications do not replicate continuous PTH secretion and, therefore, may not be consistent in correcting biochemical abnormalities and alleviating symptoms for all hypoparathyroid patients." (PMID 38562130, 2024). "Additionally, the SQRTPA defines permanent hypoparathyroidism based on the need for active vitamin D and/or calcium supplementation, without considering biochemical data on calcium and PTH levels; this differs from the definition used in the present study." (PMID 37995259, 2024). "The protective effects of PTH and PTH-related peptides on the CNS have been demonstrated in in vitro and in vivo models, but to the best of our knowledge, they have not been studied in the context of hypoparathyroidism." (PMID 38392648, 2024). "Moreover, unlike in hypoparathyroidism, the intact anti-calciuric action of PTH in the thick ascending limb is unaffected in PHP, leading to a reduced risk of hypercalciuria, even with aggressive calcium and vitamin D therapy." (PMID 39350885, 2024). "Incomplete PT adenomas resection or post-PTx persistent HPT might serve as clues of not developing HBS; however, HBS is described in cases where PTH levels decreased, but not becoming low as seen in post-PTx hypoparathyroidism." (PMID 37296804, 2023). "Postoperative serum calcium with or without PTH within 24 h was measured in almost all cases to detect whether hypoparathyroidism existed." (PMID 36835843, 2023). "The role of sex in the restoration of PTH in patients after PTG transplantation has not been reported, but multiple studies suggest that female patients are at a higher risk of developing postthyroidectomy hypoparathyroidism for TTIPA patients." (PMID 35937810, 2022). "Patients with hypoparathyroidism due to lack of PTH effects, may have an increased level of urinary calcium." (PMID 35250859, 2022). "The achievement of adequate levels of 25(OH)D3 in hypoparathyroidism may be facilitated by decreased 1α-hydroxylation as a result of the lack of PTH." (PMID 36557317, 2022). "The term ‘recovery of parathyroid function’ may be controversial but refers to the ability to wean patients off calcium and/or active vitamin D supplements without precipitating symptoms of hypoparathyroidism or a significant fall in calcium and/or PTH levels." (PMID 35389883, 2022). "A CDM analysis based on serum PTH level could objectively adjust the operational definition of hypoparathyroidism, whereas studies based on insurance claims do not provide such flexibility and rely on subjective determinations." (PMID 34640472, 2021). "Additionally, despite day 1 PTH being a reliable predictor in transient hypoparathyroidism, it did not predict permanent hypoparathyroidism." (PMID 33498810, 2021). "Patients who retained at least one well-perfused parathyroid gland (ICG 2 ≥ 1) had significantly higher PTH levels, and were less likely to develop hypoparathyroidism on postoperative day one than those without any well ICG-enhanced parathyroid gland (ICG 2 = 0) (p = 0.038)." (PMID 34575620, 2021).
hypoparathyroidism (continued). "Blood pressures were not correlated with CaXP product, PTH, Ca and P levels in the non-surgical hypoparathyroidism; however, a negative correlation was found between PTH level and diastolic blood pressure as well as mean arterial pressure in the pseudohypoparathyroidism group." (PMID 32267362, 2020). "Moreover, serum phosphate levels normalized in adult hypoparathyroid patients after continuous subcutaneous infusion of PTH(1‐34), although not in hypoparathyroid children." (PMID 32765831, 2020). "The main reason for non-inclusion was the absence of PTH levels in the medical records despite the fact that many of these patients already had a previous diagnosis of hypoparathyroidism and were receiving calcium, which forced a high number of patients with hypoparathyroidism to be excluded." (PMID 32555995, 2020). "Consequently, during long-term follow-up, 346 (96.9%) patients had normal PTH and calcium levels without symptoms of hypoparathyroidism." (PMID 29445392, 2018). "Although the time period, PTH value, and ideal protocol have not been defined yet, perioperative PTH measurements appear to be useful in the postoperative management of patients undergoing thyroidectomy who later develop hypoparathyroidism." (PMID 29694629, 2018). "However, it has been shown that some vitamin D insufficient individuals do not display increased PTH secretion and this has been termed ‘functional hypoparathyroidism’." (PMID 30723655, 2018). "Notably, a younger, sixth female sibling was also found to have mild hypoparathyroidism albeit without any electrolyte abnormality, while all other family members exhibit normal PTH and calcium levels." (PMID 28444561, 2017). "Other possibilities are a complete absence of loading but with an intact PTH cycle, e.g., injury or sickness, leading to prolonged bed rest; or a disrupted PTH cycle but with normal loading, e.g., in disease such as hypoparathyroidism, or an elderly person who is very physically active." (PMID 27379013, 2016). "Thus, chronic elevation of PTH levels increases bone resorption whereas patients with hypoparathyroidism or rodents lacking PTH exhibit reduced bone resorption." (PMID 18698360, 2008). "Both an increase in daily dietary calcium intake and sufficient PTH production by parathyroid glands may allow these patients to achieve normal calcium homeostasis under basal conditions, and disodium edetate (EDTA) infusion has been used to unmask latent hypoparathyroidism in these patients." (PMID 35432203, 2022). "One of the possible mechanisms why vitamin D3 injection may prevent TH in patients with hypoparathyroidism after TT is that increased extrarenal hydroxylation of 25-OHD independent of PTH after vitamin D3 injection may maintain serum 1, 25 hydroxyvitamin D levels." (PMID 33628238, 2021). "Thus, low PTH may have a negative influence on cognition as indicated by the two small case-control studies in hypoparathyroidism." (PMID 26010883, 2015). "Although there are no clear guidelines regarding the clinical management of hypoparathyroidism in patients with MTP defects, the available case reports suggest that these patients require periodic evaluation of blood calcium, phosphorus, and PTH levels." (PMID 41480351, 2025). "While the postoperative-1-month PTH level was higher in the TT group than that in the TT + BCND group, the incidence of protracted hypoparathyroidism did not significantly differ among the three groups." (PMID 39764252, 2024). "The postoperative-1-day PTH level was higher in the TT group than those in the TT + ICND and TT + BCND groups, whereas the incidence of immediate hypoparathyroidism was not significantly different between the TT and TT + ICND groups (25.0% vs 33.8%, P = 0.12)." (PMID 39764252, 2024). "Further studies are also suggested to evaluate the role of ferritin on PTH, FGF23 in normal population with and without hypoparathyroidism and also in other genotypes of thalassemia." (PMID 33198660, 2020).